TTF1 (transcription termination factor 1)
Diseases named in the same sentence as TTF1 in open-access papers (continued):
Sharing a sentence is not in itself a finding about the gene and the disease.
tumor (continued). "In the present case study, immunohistochemistry revealed that tumor cells exhibited positive staining for CEA and were negative for thyroglobulin and TTF-1." (PMID 23760305, 2013). "Napsin (NAPSA) was expressed in only one of the 2 AC, while TTF1 (NKX2-1) was strongly expressed in one AC, and expressed at lower levels in one ASC line, neither of these tumor markers was present in the stroma." (PMID 24324581, 2013). "The tumor cells exhibited no immunoreactivity for CKpan, CK7, CK5/6, SPA, SPB, TTF-1 and for T-cell marker CD3." (PMID 22716188, 2012). "The tumor cells were positive for chromogranin A, synaptophysin, CD57, cytokeratin (Ck), and TTF1, but staining for CD 20 was negative." (PMID 23119202, 2012). "Immunostains showed the tumor cells to be diffusely positive for CK7 and negative for CK20, WT1, D240, calretinin, CK5/6 and TTF1." (PMID 22284391, 2012). "The tumor cells were focally positive for EMA but did not stain positively for synaptophysin, chromogranin, CK7, CK20, TTF-1, GCDFP, P63 or type IV collagen." (PMID 21244696, 2011). "Immunohistochemically, tumor cells of adenocarcinoma were positive for AE1/AE3, EMA, TTF-1 and CEA, but negative for ER, PR, and Syn." (PMID 21599956, 2011). "Activated tumor cells stained intensely for MYC protein by IHC analysis and were TTF-1 positive as expected (data not shown)." (PMID 18461184, 2008). "In this case, the tumour showed diffuse positivity with antibodies to EMA, CAM 5.2, CK7, CK19 and TTF-1 and no expression (negative) with CK 20, CEA, S-100 protein, thyroglobulin, SMA and p63." (PMID 18492272, 2008). "The tumor cells were non-immunoreactive for cytokeratin 7, cytokeratin 20, cocktail of cytokeratin AE1/AE3 – Cam 5.2, thyroid transcription factor (TTF-1), leucocyte common antigen (LCA, CD45), and MART-1." (PMID 15967023, 2005). "Thyroid transcription factor-1 (TTF-1) immunostaining may assist in determining the tumor origin; for example, a pulmonary NET metastatic to the thymus would typically be TTF-1-positive, whereas a primary thymic carcinoid is usually TTF-1-negative." (PMID 40563625, 2025). "In addition, in contrast to the 68 SEGAs previously analyzed, the tumor cells were uniformly negative for TTF‐1, using either clone SPT24 or clone 8G7G3/1 of the antibody against TTF‐1." (PMID 39492623, 2025). "In our investigation of LUAD, our findings demonstrated significantly increased expression levels of PSMD14, TTF1, KI67, CK7, and NapsinA in tumor tissues when compared to adjacent non-cancerous tissues, further supporting the role of PSMD14 across various cancer types." (PMID 40475775, 2025). "The tumor cells were positive for CA125 andHNF1β but negative for thyroglobulin, TTF-1 and PAX8." (PMID 39700333, 2024). "The tumor was positive for CK7 and CA19-9 and negative for CK20, HAS and TTF1." (PMID 37404765, 2023). "Furthermore, the low-grade tumor in the fallopian tube was negative for CDX2 and TTF1, which led us to believe that it was a primary NET." (PMID 36178284, 2023). "The tumour was GATA3-, CK5-, CK14- and CK7-positive and TTF1-negative." (PMID 37760817, 2023).
tumor (continued). "This tumor is characterized by comprising two types of tumor cells, including surface epithelial cells expressing pan-CK and TTF-1 and stromal round cells expressing TTF-1 and EMA but negative for CK." (PMID 36759857, 2023). "Immunohistochemistry showed that the tumor cells were diffusely positive for SF-1 and Ki-67, partially positive for inhibin, and negative for CAM5.2, CK7, CK20, C-KIT, CD30, LCA, GATA-3, TTF-1, and PAX8." (PMID 36335378, 2022). "While tumour weights and volumes were not significantly higher in LAM1:PIK3CAE545K mice, there was a decrease in expression of thyroid differentiation markers TTF-1, thyroglobulin, PAX8 and B-catenin, suggesting that introduction of PIK3CAE545K led to dedifferentiation in vivo." (PMID 35193694, 2022). "The tumor was positive for synaptophysin, CAM 5.2 and CD56 and negative for CD19 and TTF-1." (PMID 34391482, 2021). "Immunostains showed the cells had patchy positivity for Pax‐8 and GATA‐3, and focal weak positivity for pancytokeratin and p63, while they were negative for TTF‐1, CK7, CK20, CA‐IX, and 34‐beta‐E‐12, compatible with a metastasis from a sarcomatoid neoplasm of renal origin." (PMID 32463173, 2020). "Tumor cells express CK7 and TTF-1, but do not express P40 and other basal cell markers." (PMID 33282636, 2020). "Final diagnosis was confirmed by immunohistochemical (IHC) analysis which revealed that the tumor cells were positive for neuroendocrine markers, such as CD56, chromogranin A, synaptophysin, Cytokeratin (CK), and thyroid transcription factor (TTF-1) but negative for D2–40, CK20, CDX2, and HBME1." (PMID 31770288, 2019). "Singh K showed that the tumor cells are positive for calcitonin, HMB-45, carcinoembryonic antigen (CEA), syn, chromogranin, vimentin, and epithelial membrane antigen and negative for TG, S-100, melan A, and TTF-1." (PMID 30424779, 2018). "The tumor cells were negative for CK20 and CDX2 and positive for CK7, TTF1, and PAX8 markers." (PMID 30087814, 2018). "There is no clear explanation for this observation; however, we cannot exclude that the expression of TTF-1 and CD56 molecules in CTCs are not related with the invasive potential or the aggressivity of tumor cells in contrast with the more epithelial EpCAM+/CK+ CTCs detected by CS." (PMID 28349943, 2017). "Further immunohistological analysis of the metastastic tissue showed no staining for TTF-1, CD10 or ChrA (data not shown) as expected since the scattered small cell component that is seen throughout the tumor appears to be a less differentiated part of the chRCC." (PMID 28499369, 2017). "Tumor cells were positive for CK7 EMA, CKAE1/AE3, CD15, CA-125, while immunoreaction for Calretinin, WT1, estrogen, and progesterone receptors, cytokeratin 20, CD10, alpha fetoprotein, CDX2, TTF1, and thyroglobulin were all negative." (PMID 27912770, 2016). "However, cytokeratin, calcitonin, CEA, and TTF1 positivities, which are frequently observed in MTC but not in PGLs, help to distinguish these two different tumor types." (PMID 27066280, 2016). "The tumor cell test results were positive for CK20 and negative for CK7 and TTF-1." (PMID 27714647, 2016). "TTF-1, thyroglobulin, calcitonin, CK20 and CK7 were negative in metastatic tumour areas." (PMID 22933935, 2011). "Pathologists should be aware that the three routinely used TTF‐1 antibody clones 8G7G3/1, SPT24, and SP141 have different sensitivity and specificity and can therefore result in variable distribution and intensity of immunohistochemical stain, or even in nonspecific staining of other tumor types." (PMID 39350562, 2025).
tumor (continued). "By immunohistochemistry, the tumor cells expressed synaptophysin, chromogranin, NKX2.2 (diffuse, nuclear), GFAP (patchy), SMI31 (neurofilament) (focal, cytoplasmic), and TdT (diffuse, nuclear), while lacking expression of CD99, TTF-1, CK 20, MCPyV, PHOX2B, Olig2, OCT3/4, CD45, CD3 and PAX5." (PMID 38031161, 2023). "Most tumor cells of the neuroendocrine component were immunoreactive for CAM.5.2, cytokeratin (CK) 7, CK AE1/AE3, synaptophysin, chromogranin A, parathormone, GATA3, and parafibromin, whilst they were negative for thyroglobulin, TTF1, calcitonin, glucagon, and S100." (PMID 32506375, 2021). "In addition to the antigens described here, the original tumor was positive for CKC, CK7 and CK 5/6, negative for GATA3, CDX2, ERα, CK20,p63, AFP, CA19.9, TTF1 and PAX 8 and with patchy/focal staining for calretinin, CD10, RCC, BerEP4 and WT‐1 (data not shown)." (PMID 30109783, 2018). "The tumor was biopsied via bronchoscopy and found to be a poorly differentiated carcinoma, which was strongly positive for cytokeratin 7 (CK7), carcinoembryonic antigen (CEA), and thyroid transcription factor-1 (TTF-1) but negative for CK20, estrogen receptor, and progesterone receptor." (PMID 29900025, 2017).
adenocarcinoma (291 papers, 2003 to 2026). A common cancer characterized by the presence of malignant glandular cells. "Clinically, TTF-1 serves as a diagnostic biomarker to differentiate LUAD from other adenocarcinoma metastases of extra-thoracic origin." (PMID 39630375, 2025). "As expected, TTF-1 expression was significantly associated with adenocarcinoma histology (p < 0.001)." (PMID 40647486, 2025). "In NSCLC, particularly adenocarcinoma, TTF-1 expression has long been associated with favorable prognosis and enhanced sensitivity to pemetrexed-based chemotherapy." (PMID 40647486, 2025). "TTF-1 and Napsin A expression were significantly associated with adenocarcinoma (p < 0.001), while p40 and p63 expression were significantly associated with SCC (p < 0.001)." (PMID 40746930, 2025). "TTF1 expression, a diagnostic marker for adenocarcinoma, was consistent primarily in early and intermediate PDX passages, while P40 positivity, a marker for squamous cell differentiation, varied throughout generations of PDXs." (PMID 38553659, 2024). "Further, we assessed potential amplification of the NKX2-1 gene, which encodes for TTF1, a biomarker that distinguishes adenocarcinomas." (PMID 37634047, 2023). "In accordance with the immunohistochemical findings, all these cases were defined as solid variant adenocarcinomas with unusual coexpression of TTF-1 and p63." (PMID 31935792, 2020). "The other cases of PD-NSCLC, despite the positivity for CK5/6, were diagnosed as “adenocarcinoma, solid variant”, in keeping with the presence of TTF-1 expression and p40 negativity." (PMID 31935792, 2020). "Among our patients (48 men and 2 women) all adenocarcinoma (confirmed by histology and IHC with TTF1/Napsin A), 94% were smokers exceeding the tobacco risk threshold (at least 25 pack-years) and the women were none." (PMID 30092812, 2018). "And some studies also revealed the relationship between TTF-1 expression and gene mutations that a higher epidermal growth factor receptor (EGFR) mutation rate would be found in TTF-1 positive adenocarcinoma." (PMID 29296178, 2017). "A higher EGFR mutation rate was identified in TTF-1+ adenocarcinomas, but a fraction of TTF-1− adenocarcinomas still had EGFR mutation." (PMID 29296178, 2017). "Concerning NSCLC, TTF-1-expression is associated with better overall survival, which is even more pronounced in the subgroup of patients with adenocarcinoma." (PMID 25889870, 2015). "Though mutations in EGFR are thought to be a driver in adenocarcinomas, it is possible that TTF-1 (being a transcription factor) facilitates the transcription of necessary genes to maintain survival signaling and evade apoptosis." (PMID 25594059, 2014). "Immunohistochemical markers TTF-1 and Napsin A are nowadays a useful tool in adenocarcinoma identification and their dual use improves diagnostic accuracy, but does not give us data about prognosis of cancer which often has high metastatic potential." (PMID 23190601, 2012). "Here, MAdL as a new and specific marker for adenocarcinomas of the lung offers a diagnostic benefit of 16% if used as a second-line marker besides TTF-1." (PMID 21811254, 2011). "This gene encodes for the well known TTF1 (Thyroid transcription factor), a protein which is expressed in normal lung and thyroid tissues and in their related adenocarcinomas." (PMID 19594952, 2009). "Furthermore, the positive ratio of TTF-1 is significantly associated with the degree of differentiation within adenocarcinoma tissues." (PMID 40575170, 2025). "The association of TTF-1 expression with prognosis in stage I adenocarcinoma is unclear." (PMID 29296178, 2017). "TTF-1 staining was associated with adenocarcinoma histology (p<0.0001)." (PMID 26208325, 2015). "Almost all (145/148; 98.0%) mutated adenocarcinomas were TTF-1 positive." (PMID 23934203, 2013). "Lung biopsy confirmed TTF-1 and Napsin A-positive adenocarcinoma, and genomic profiling identified an ERBB2 (HER2) exon 20 insertion mutation (p.A775_G776insYVMA; VAF 3.9%)." (PMID 42058342, 2026).
adenocarcinoma (continued). "Biopsy confirmed adenocarcinoma (thyroid transcription factor-1 (TTF-1) +, Programmed Death-Ligand 1 (PD-L1) >80%), and next-generation sequencing revealed a MET exon 14 skipping mutation." (PMID 41573491, 2025). "Bronchoscopy was non-diagnostic, while CT-guided transthoracic biopsy confirmed a moderately differentiated adenocarcinoma, positive for thyroid transcription factor-1 (TTF-1)." (PMID 41573491, 2025). "The p-value for TTF-1 expression in adenocarcinoma was 0.000, indicating high statistical significance." (PMID 40746930, 2025). "Pathological evaluations showed that LAC-TB and LAC groups expressed TTF-1 and Napsin A in their adenocarcinoma specimens." (PMID 40061944, 2025). "Immunohistochemically, adenocarcinomas are usually positive for markers such as thyroid transcription factor-1 (TTF-1) and Napsin A." (PMID 41303058, 2025). "The remaining eight cases, which were negative for both p40 and p63, exhibited nuclear positivity for TTF-1 and cytoplasmic staining for Napsin A. Based on this immunoprofile, these eight cases were reclassified as adenocarcinoma." (PMID 40746930, 2025). "PD-L1 expression was distributed as <1% in 31.7%, 1–49% in 38.3%, and ≥50% in 30.0%, with thyroid transcription factor-1 (TTF-1) positive in 69.2% of adenocarcinomas." (PMID 40941007, 2025). "Among malignant tumors, for which expression of TTF-1 has been reported, adenocarcinomas of the gastrointestinal tract deserve a special mention." (PMID 40564811, 2025). "(2022) reported that female gender correlates with TTF-1/Napsin A co-expression in adenocarcinoma, supporting the role of sex-specific biological pathways in alveolar epithelial differentiation." (PMID 40687424, 2025). "Loss of SMARCA2 and SMARCA4 was frequent in solid-predominant adenocarcinomas and tumors with low levels of bronchial epithelial markers, i.e., TTF-1, CK7, and E-cadherin." (PMID 39888726, 2025). "Unlike SMARCA4-UT, NSCLC with SMARCA4 deficiency usually shows cohesive fragments of malignant cells with at least focal adenocarcinoma or squamous cell differentiation, which can be confirmed with TTF-1, p63/p40, or keratin IHC stains." (PMID 40406754, 2025). "For adenocarcinomas, excluding NENs, TTF1 positivity was highly useful in identifying pulmonary origin." (PMID 40751531, 2025). "Mucicarmine stain, thyroid transcription factor‐1 (TTF‐1) and Napsin A support an adenocarcinoma component and P40 supports squamous differentiation." (PMID 39311155, 2025). "Immunohistochemical staining for TTF-1 and Napsin A is commonly employed to confirm adenocarcinoma lineage, especially in poorly differentiated tumors where morphology alone is insufficient." (PMID 41303058, 2025). "Pathological evaluation postresection revealed metastatic moderately differentiated adenocarcinoma with immunohistochemical (IHC) features (CK20+/Villin+/CK7−/TTF-1−) suggestive of GI origin." (PMID 40703540, 2025). "According to the results of exfoliative cytology of drainage fluid and immunohistochemistry [CK (AE1/AE3) (+), CK56 (−), CD68 (−), CD45 (LCA) (−), TTF-1 (+), p40 (+), D2-40 (−), and ki-67 (50%+)], adenocarcinoma of lung origin was considered." (PMID 39928773, 2025). "It is important to note that this positivity of p63 and TTF-1 should be seen in the same population to be regarded as adenocarcinoma, while if it is in different populations, it is interpreted as adenosquamous." (PMID 39070322, 2024). "We encountered a case of adenocarcinoma with a papillary pattern, which turned out to be TTF-1 and p63-positive." (PMID 39070322, 2024). "In the current study, TTF1 was found to have a sensitivity of 97.6% among poorly differentiated adenocarcinomas, while it was 86.6% in the well-differentiated group." (PMID 39584166, 2024). "On immunostains, tumoral cell positivity for TTF1 and napsin A suggested a malignity with a pulmonary phenotype, compatible with the diagnosis of adenocarcinoma with signet ring features." (PMID 38256374, 2024).